RAP1B (RAP1B, member of RAS oncogene family)
Diseases named in the same sentence as RAP1B in open-access papers (continued):
Sharing a sentence is not in itself a finding about the gene and the disease.
chondrosarcoma (1 paper, 2024). A malignant cartilaginous matrix-producing mesenchymal neoplasm arising from the bone and soft tissue. "We need to better understand how miR-518b works with Rap1b, and what role this relationship could play in the development and progression of chondrosarcoma." (PMID 38542153, 2024).
choroidal neovascularization (1 paper, 2013). An eye disorder described by the growth of new blood vessels that originate from the choroid through a break in the Bruch membrane into the sub–retinal pigment epithelium (sub-RPE) or subretinal space. "In a laser-induced choroidal neovascularization (CNV) model of macular degeneration, Rap1b−/− mice exhibited larger CNV volumes compared to wild-type or Rap1a−/−." (PMID 24039860, 2013).
endothelial dysfunction (1 paper, 2021). In vascular diseases, endothelial dysfunction is a systemic pathological state of the endothelium (the inner lining of blood vessels) and can be broadly defined as an imbalance between vasodilating and vasoconstricting substances produced by (or acting on) the endothelium. "Here, we demonstrate that endothelial dysfunction resulting from knockout of both Rap1A and Rap1B isoforms is ameliorated by exogenous L-Arg administration to rescue NO-dependent vasorelaxation and blood pressure." (PMID 34222255, 2021).
focal segmental glomerulosclerosis (1 paper, 2022). A renal disorder characterized by sclerotic lesions in the glomeruli. "In mice, knockout of Rap1A and Rap1B results in disruption of slit diaphragm integrity and development of focal segmental glomerulosclerosis (FSGS)." (PMID 35372328, 2022). "In mice, knockout of Rap1A and Rap1B results in disruption of slit diaphragm integrity and development of focal segmental glomerulosclerosis (FSGS)—a chronic glomerular disease with scarring, sclerotic lesions." (PMID 35372328, 2022).
heart failure (1 paper, 2013). Inability of the heart to pump blood at an adequate rate to meet tissue metabolic requirements. "RAP1B, a platelet GTPase, was significantly reduced 180 months days following LVAD placement, while expression pre-LVAD and 7 days post was not significantly different from non-heart failure controls." (PMID 24205042, 2013).
Immunodeficiency (1 paper, 2024). Failure of the immune system to protect the body adequately from infection, due to the absence or insufficiency of some component process or substance. "We report a boy with neonatal thrombocytopenia, combined immunodeficiency, neutropenia, and monocytopenia caused by a heterozygous de novo single nucleotide substitution, c.35G>A (p.G12E) in RAP1B." (PMID 39225097, 2024). "Our findings define monoallelic RAP1B gain-of-function variants as a cause for constitutive immunodeficiency and thrombocytopenia." (PMID 39225097, 2024).
infertile (1 paper, 2014). "The increased expression of Rap-1b in mid-secretory phase of infertile women may be because of altered- or dysregulated- progesterone signalling and might also involve RAS/RAF/MAPK and PI3K pathways." (PMID 25405865, 2014).
Kabuki syndrome (1 paper, 2024). Kabuki syndrome (KS) is a multiple congenital anomaly syndrome characterized by typical facial features, skeletal anomalies, mild to moderate intellectual disability and postnatal growth deficiency. "RAP1A and RAP1B dysfunction results in aberrant MEK/ERK signaling, indicating an overlap in the pathophysiology of Kabuki syndrome caused by these genes and the RASopathies." (PMID 38667491, 2024). "Recent studies have identified additional genes associated with Kabuki syndrome, including RAP1A, RAP1B, and HNRNPK." (PMID 38667491, 2024). "Thus, a comprehensive screening of other genes associated with Kabuki syndrome (e.g., KDM6A, RAP1A, RAP1B, and HNRNPK) was not performed." (PMID 38667491, 2024).
leukemia (1 paper, 2021). A malignant (clonal) hematologic disorder, involving hematopoietic stem cells and characterized by the presence of primitive or atypical myeloid or lymphoid cells in the bone marrow and the blood. "However, the expression of Rap1b was found in breast, colorectal, leukemia, lung, ovarian and prostate was decreased." (PMID 34346294, 2021).
Macrothrombocytopenia (1 paper, 2022). "We have previously shown that mice deficient in both Rap1a and Rap1b exhibit a marked macrothrombocytopenia due to a defect in PPF and that this activity of Rap1 is not dependent on its ability to bind talin and activate integrins." (PMID 35290242, 2022). "Simultaneous loss of Rap1a and Rap1b further prolongs bleeding times; it also causes macrothrombocytopenia due to impaired platelet production." (PMID 35290242, 2022). "Macrothrombocytopenia was recently also reported for 2 patients with GOF mutations in RAP1B." (PMID 35290242, 2022).
monocytopenia (1 paper, 2024). "In conclusion, we demonstrate that P1’s monoallelic RAP1B-G12E is a de novo somatic mutation causing CID and severe thrombocytopenia associated with neutropenia and monocytopenia." (PMID 39225097, 2024). "We identified a de novo heterozygous single nucleotide substitution c.35G>A in RAP1B, p.G12E, in a 2-year-old boy with an undescribed hematological disorder associated with CID, neutropenia, and monocytopenia as well as severe thrombocytopenia and platelet dysfunction." (PMID 39225097, 2024).
Obesity (1 paper, 2019). Accumulation of substantial excess body fat. "MRNA levels of Rap1a and Rap1b were unaffected by diet-induced obesity whereas expression of Rab3a was slightly reduced." (PMID 31337827, 2019).
preeclampsia (1 paper, 2018). Preeclampsia is a hypertensive disorder of pregnancy that is characterized by new-onset hypertension with proteinuria presenting after 20 weeks of gestation, and depending on mild or severe forms may initially present with severe headache, visual disturbances, and hyperreflexia. "In general, this study demonstrated the regulation of trophoblast cell invasion by miR-518b–Rap1b–Ras–MAPK pathway, and supported a possible role in the development of preeclampsia although further work is required." (PMID 29599749, 2018).
primary immunodeficiency (1 paper, 2024). "Our findings illustrate the phenotypic continuum of monoallelic RAP1B GOF variants ranging from isolated primary immunodeficiency and thrombocytopenia in a patient with somatic mosaicism to complex syndromic features in patients with germline mutations." (PMID 39225097, 2024). "Thus, our study defines monoallelic GOF RAP1B variants as cause for primary immunodeficiency associated with thrombocytopenia." (PMID 39225097, 2024).
renal carcinoma (1 paper, 2016). A carcinoma arising from the epithelium of the renal parenchyma or the renal pelvis. "In vitro gain-of-function and loss-of-function studies in human renal carcinoma cell lines, demonstrated that miR-28-5p suppressed cell proliferation and migration by directly inhibiting RAP1B, and this effect was reversed by co-transfection with RAP1B." (PMID 27729617, 2016). "The recombinant wild type RAP1B 3′-UTR constructs or mutant 3′-UTR constructs were transfected into human renal carcinoma cell lines A498 and ACHN together with miR-28-5p mimics or negative controls." (PMID 27729617, 2016). "We furthermore assessed the possible role of RAP1B on the migratory capacity of renal carcinoma cells." (PMID 27729617, 2016). "We evaluated the effects of RAP1B on renal carcinoma cell proliferation using the CCK-8 assay after transfecting A498 and ACHN cells with synthesized specific small interfering RNAs (siRNAs) against RAP1B mRNA or a RAP1B–expression vector." (PMID 27729617, 2016). "Functional studies showed that RAP1B has an opposite effect to that of miR-28-5p in the regulation of renal carcinoma cell proliferation and migration in vitro and also has an opposite effect to that of miR-28-5p in xenograft tumor growth in vivo." (PMID 27729617, 2016). "In RCC tissues and renal carcinoma cells, miR-28-5p is expressed at a low level and RAP1B is expressed at a high level." (PMID 27729617, 2016). "Taken together, these results combined with the results of the in vitro assays, which confirmed the tumor suppressor role of miR-28-5p in renal carcinoma tumorigenesis through the targeting of RAP1B." (PMID 27729617, 2016). "Transfection of miR-28-5p mimics inhibited RAP1B protein expression in renal carcinoma cells, and transfection of miR-28-5p inhibitor promoted RAP1B protein expression." (PMID 27729617, 2016). "Collectively, our data strongly suggest that RAP1B and miR-28-5p have opposing effects on the regulation of renal carcinoma cell migration." (PMID 27729617, 2016). "In the meanwhile, we also observed that the average tumor volume was about two fold greater in the mice inoculated with A498 cells overexpressing RAP1B compared to the control mice (P < 0.01), and these results indicate that RAP1B acts as a promoter of renal carcinoma growth." (PMID 27729617, 2016). "Thus, we tested whether the suppression of the expression of RAP1B resulted by miR-28-5p overexpression affects the activation of these two MAP kinases in renal carcinoma cells." (PMID 27729617, 2016). "However, it is possible that other potential targets of miR-28-5p in addition to RAP1B may be involved in the regulation of renal carcinoma cell proliferation and migration." (PMID 27729617, 2016). "The RAP1B protein level was increased in RCC tumor specimens and renal carcinoma cell lines, and this was inversely correlated with miR-28-5p expression." (PMID 27729617, 2016). "Our study is the first to show that RAP1B is upregulated in RCC tumor samples and several renal carcinoma cell lines." (PMID 27729617, 2016). "To confirm whether RAP1B acts as an oncoprotein in RCC, we examined the effects of RAP1B on renal carcinoma cell proliferation in vitro." (PMID 27729617, 2016).
squamous carcinomas (1 paper, 2017). "RAP1B represents an example where high CN gain of both adeno- and squamous carcinomas is associated with high gene expression." (PMID 29112949, 2017).
Thrombocytopenia (1 paper, 2024). A reduction in the number of circulating thrombocytes. "Heterozygous germline RAP1B variants have been described in patients with syndromic thrombocytopenia." (PMID 39225097, 2024). "Deficiency of a single Rap1 protein is associated with an intermediate platelet phenotype, more severe for Rap1b than for Rap1a deficiency, whereas Rap1a/b–double-knockout in a murine megakaryocyte model leads to severe thrombocytopenia and platelet dysfunction." (PMID 39225097, 2024). "RAP1B-G12E is associated with severe thrombocytopenia and abnormal platelet function." (PMID 39225097, 2024).
thyroid (1 paper, 2012). "Regarding the selected genes in other CNA/UPD areas, the AKT3/PIK3CA pathway, the KRAS/RAP1B/RAP1GAP/BRAF pathway, and the VEGFC pathway have been known to participate in thyroid carcinogenesis/cancer progression." (PMID 22558328, 2012).
uveal melanoma (1 paper, 2025). A melanoma derived from melanocytes of the uveal tract. "The STRING analysis performed in plasma samples of uveal melanoma patients for miR-155-5p showed that the molecules with the most interaction of the miR-155-5p were CBL and RAP1B proteins along with FOS and ETS1 (p value: 0.000399)." (PMID 38914847, 2025).
tumor (40 papers, 2009 to 2026). "Supporting its relevance as a therapeutic target, single-cell transcriptomic analyses have identified elevated Rap1B expression in tumor-associated endothelial cells across multiple cancers, including lung, colorectal, and ovarian tumors." (PMID 40508181, 2025). "Even when Rap1B-deficient tumor ECs are treated with TNF-α, VEGF-A cannot suppress TNF-α-induced expression of ICAM1 or VCAM1." (PMID 39337337, 2024). "Rap1B is a small protein that activates multiple signaling cascades associated with tumor development and progression." (PMID 35207103, 2022). "RAP1B is a ras-related-protein, and the tumor with amplification of RAP1B also had a point mutation affecting the amplified allele." (PMID 34272401, 2021). "The results showed that in addition to ESCA, GBM, SARC and UCS, Rap1b was significantly associated with MMR gene expression in 29 tumor types." (PMID 34346294, 2021). "Functional analyses of miR-28-5p revealed tumor suppressive properties caused by the inhibition of Rap1b, E2F6, IGF-1, IL-34, and AKT." (PMID 31921670, 2019). "RAP1B activates multiple signaling cascades associated with tumor development and progression and is involved in cell proliferation, invasion, cell adhesion and angiogenesis." (PMID 27729617, 2016). "Specifically, overexpression of SNORA70E enhances tumour cell propagation, invasion, and migration in vitro, driving tumour progression via pseudouridylation of RAP1B and alternative splicing of PARPBP in ovarian cancer." (PMID 39834094, 2025). "While targeting Rap1B offers therapeutic potential, especially in the tumor microenvironment, its essential role in endothelial NO production and vascular homeostasis necessitates caution." (PMID 40508181, 2025). "While most studies have focused on tumor or platelet systems, direct targeting of Rap1A and Rap1B by miRNAs has also been demonstrated in endothelial cells." (PMID 40508181, 2025). "Rap1B has emerged as a context-dependent regulator of tumor vascular function, promoting both angiogenesis and immune evasion through VEGF–VEGFR2 signaling (see Section 3.1.1 and Section 3.3.1)." (PMID 40508181, 2025). "By promoting angiogenesis and inhibiting leukocyte recruitment, tumor EC Rap1B significantly influences EC responses in the TME." (PMID 39337337, 2024). "Elevated in tumor ECs, Rap1B promotes tumor growth by enhancing VEGFR2 activity and contributing to vascular immunosuppression, which impedes immune cell infiltration." (PMID 39337337, 2024). "Recent studies show that Rap1B in tumor endothelium mediates VEGF-mediated vascular immunosuppression, raising the exciting possibility of being a novel target in anti-angiogenesis therapy, as detailed in the next section." (PMID 39337337, 2024). "Many of theseDEPs have been suggested as potential clinical prognostic markers,due to their functional association with tumor growth and progression.32−37 We found upregulation of MUC1 and RAP1B in LUAD pEV samples comparedwith the MM pEV samples." (PMID 39141927, 2024). "These inhibitors aim to disrupt Rap1B function, normalize tumor vasculature, and enhance immune cell infiltration, ultimately leading to more effective cancer therapies." (PMID 39337337, 2024). "In our study, the oncogenic roles of DLEU2 and RAP1B in OC and the tumor suppressor role of miR-30a-5p were first determined." (PMID 36277988, 2022). "Upregulation of miR-128 attenuated GBM tumor progression by targeting the cytoskeleton and related Rap1B-mediated molecular changes." (PMID 36793341, 2022). "Rap1B is inhibited at the post-transcriptional level by some tumor suppressor miRNAs, such as miR-518b in squamous cell carcinoma of the esophagus and by miR-139 and miR-100 in colorectal cancer." (PMID 35207103, 2022).
tumor (continued). "It will affected the results to a certain extent, so subsequent experiments in vivo or in vitro are needed to verify and clarify the correlation of Rap1b expression with tumor immune infiltration." (PMID 34346294, 2021). "SangerBox database was used to analyzed the correlations between Rap1b expression and immune checkpoint (ICP), tumor mutational burden (TMB), microsatellite instability (MSI), mismatch repairs (MMRs) and DNA methylation." (PMID 34346294, 2021). "Accordingly, MALAT1 expression enhanced tumor proliferation by upregulating Rap1b and zinc-fingers and homeoboxes 1 (ZHX1) by sponging miR-101 in glioma and miR-199a in glioblastoma, respectively." (PMID 34322395, 2021). "Correlation between Rap1b expression and Immune Checkpoint (ICP) Genes, Tumor Mutational Burden (TMB), Microsatellite Instability (MSI), mismatch repairs (MMRs) and DNA methylation." (PMID 34346294, 2021). "Meanwhile, Rap1b was correlated closely with tumor immunity and interacted with various immune cells in different types of cancers." (PMID 34346294, 2021). "The relationship between Rap1b expression and checkpoint gene expression in tumor immune response was further analyzed from mRNA sequence database." (PMID 34346294, 2021). "Ras-related Protein Rap1b expression was corelated with poor prognosis and tumor immune infiltration in pan-cancer." (PMID 34486492, 2021). "Sponging miR-101 not only enhanced tumor proliferation by upregulating Rap1b, but also induced higher expression of autophagy-associated genes (Stathmin 1, RAB5A, and ATG4D)." (PMID 34322395, 2021). "Rap1b was correlated closely with tumor immunity and interacted with various immune cells in different types of cancers." (PMID 34346294, 2021). "We then investigated the potential correlations of Rap1b expression with immune infiltration based on the Tumor Immune Estimation Resource (TIMER)." (PMID 34346294, 2021). "In conclusion, the results of pan-cancer analysis showed that the abnormal Rap1b expression was related to poor prognosis and tumor immune infiltration in different cancers." (PMID 34346294, 2021). "In conclusion, these results collectively demonstrated that LINC00514 acted as a key tumor promotor of PC by competitively binding to miR-28-5p and then upregulating the expression of Rap1b." (PMID 32771045, 2020). "It was found that only RAP1B expression was significantly increased in ESCA tumor samples (p=2.3529e − 4)." (PMID 33061972, 2020). "Mir-518b has been shown to suppress cell proliferation by inducing apoptosis in tumor cells and invasion by targeting Rap1b." (PMID 28182660, 2017). "Gain-of-function and loss-of-function studies demonstrated that miR-28-5p acted as a tumor suppressor in RCC for multiple antitumor effects by directly inhibiting RAP1B." (PMID 27729617, 2016). "The cell proliferation rate, as measured by the ratio of Ki-67 and PCNA positive tumor cells, were increased in tumors from the RAP1B-overexpressing group and decreased in tumors from the miR-28-5p-overexpressing group." (PMID 27729617, 2016). "Recently, some studies have shown that RAP1B expression is inhibited at the post- transcriptional level by some tumor suppressor miRNAs." (PMID 27729617, 2016). "Because our in vitro experiments revealed that miR-28-5p or RAP1B expression was associated with proliferative traits, we next examined the effect of miR-28-5p or RAP1B expression on tumor formation in vivo." (PMID 27729617, 2016). "We performed a tumor formation assay in a nude mouse model using A498 cells stably expressing miR-28-5p after lentiviral infection or transfected with a RAP1B plasmid to overexpress RAP1B, and then cells were implanted subcutaneously into mice." (PMID 27729617, 2016). "Recently, some studies have documented RAP1B regulation at the post-transcriptional level by some tumor suppressor miRNAs." (PMID 27729617, 2016).